POR (cytochrome p450 oxidoreductase)
Diseases named in the same sentence as POR in open-access papers (continued):
Sharing a sentence is not in itself a finding about the gene and the disease.
hypoglycaemia (2 papers, 2018 to 2021). "In conclusion, we have shown that interaction between the CYP2C9 and POR genes affects the risk of SU‐induced hypoglycaemia and the efficacy of SU treatment." (PMID 28656666, 2018). "Consistent with the effect on hypoglycaemia, the interaction between CYP2C9 and POR genes also showed an association with the efficacy of SU treatment, assessed as a combined outcome of HbA1c reduction and prescribed SU daily dose." (PMID 28656666, 2018). "Another small study suggested a possible interaction between P450 oxidoreductase (POR) and CYP2C9 genotypes, where POR*28 allele could mask the effect of CYP2C9*2 allele on sulfonylurea-induced hypoglycemia." (PMID 34194474, 2021).
Menstrual disorder (2 papers, 2017 to 2023). Category of disorders related to menstruation. "In addition, the loss of POR enzyme activity varies with POR mutation type; thereby, PORD has a variety of clinical manifestations from menstrual disorders to severe hermaphroditism and skeletal malformations, and even fetal death." (PMID 28288674, 2017).
osteosarcoma (2 papers, 2023 to 2024). A usually aggressive malignant bone-forming mesenchymal neoplasm, predominantly affecting adolescents and young adults. "A novel POR regulator, Zoledronic acid, was shown to increase ROS and lipid peroxidation levels in osteosarcoma cells through ferroptosis activation; it was also observed to be able to inhibit osteosarcoma growth in vivo using a BALB/c nude mice xenograft model." (PMID 37132605, 2024). "In osteosarcoma, zoledronic acid can induce ferroptosis by decreasing ubiquinone and upregulating the expression of HMOX1 or cytochrome P450 oxidoreductase (POR)." (PMID 37388742, 2023).
ovarian carcinoma (2 papers, 2024). A malignant neoplasm originating from the surface ovarian epithelium. "miR-214 offers protection against oxidative damage by targeting GSR and cytochrome P450 oxidoreductase (POR) and is involved in cell survival, embryonic development, and ovarian cancer resistance." (PMID 39334761, 2024).
prostate carcinoma (2 papers, 2021 to 2022). A carcinoma that arises from epithelial cells of the prostate gland. "The biological assessment included CYP17A1 hydroxylase and lyase inhibition, CYP3A4 and P450 oxidoreductase (POR) inhibition, as well as antiproliferative activity in PC3 prostate cancer cells." (PMID 35204665, 2022).
viral diseases (2 papers, 2024 to 2025). "By contrast, POR, CNTN2, and HSD17B10 have not previously been associated with viral diseases." (PMID 41303479, 2025).
amenorrhea (1 paper, 2024). The absence of menses in a woman who has achieved reproductive age. "The involvement of Cytochrome P450 oxidoreductase in drug metabolism has enabled linking Antley–Bixler syndrome and amenorrhea to fluconazole consumption in mothers with Cytochrome P450 oxidoreductase mutations, an enzyme crucial for the function of specific other enzymes." (PMID 39533614, 2024).
Anxiety (1 paper, 2022). Intense feelings of nervousness, tension, or panic often arise in response to interpersonal stresses. "Our study highlights the associations between neuroticism with C1-INH and POR, and may provide novel insights to uncover the roles of protein on the development of depression, anxiety and neuroticism." (PMID 35870967, 2022).
autoimmune disease (1 paper, 2024). A disorder resulting from loss of function or tissue destruction of an organ or multiple organs, arising from humoral or cellular immune responses of the individual to their own tissue constituents. "POR had strong evidence for colocalization with autoimmune diseases at rs59882870 (PP.H4 = 1.00), which reinforced the causal effect of POR on autoimmune diseases." (PMID 38685026, 2024). "Furthermore, intermediate analyses revealed that air pollutants increased the risk of autoimmune diseases by modulating the expression of POR, HSPA1B, SHANK3, and BRD2." (PMID 38685026, 2024). "Then, we performed mediation analyses, which showed that POR, HSPA1B, SHANK3, and BRD2 might exert mediating effects from air pollutants to increased risk of autoimmune diseases." (PMID 38685026, 2024). "POR pQTL (rs59882870, PPH4=1.00) strongly colocalized with autoimmune diseases." (PMID 38685026, 2024).
ciliopathy (1 paper, 2021). A genetic disorder of the cellular cilia or the cilia anchoring structures, the basal bodies, or of ciliary function. "Our protein‐protein interaction network analysis revealed that POR, but not CD166, interacted with either established or strong ciliopathy gene candidates." (PMID 33936569, 2021).
Crouzon syndrome (1 paper, 2018). Crouzon disease is characterized by craniosynostosis and facial hypoplasia. "A patient in our hospital who was previously diagnosed as Crouzon syndrome was finally proved to be Cytochrome P450 oxidoreductase deficiency by NGS." (PMID 30687093, 2018).
development (1 paper, 2014). "Influence of POR variants found in patients with disorder of sexual development, on the enzyme activities of its redox partners." (PMID 24847272, 2014).
Fine-Lubinsky syndrome (1 paper, 2023). A syndrome characterized by psychomotor delay, brachycephaly with flat face, small nose, microstomia, cleft palate, cataract, hearing loss, hypoplastic scrotum and digital anomalies. "Two patients referred with Fine Lubinsky syndrome and found to have pathogenic variants in POR and SLC39A13, respectively, had their clinical diagnoses changed to Antley-Bixler and spondylocheiro-dysplastic Ehlers-Danlos syndromes, respectively." (PMID 37946251, 2023).
G6PD deficiency (1 paper, 2025). An X-linked genetic condition caused by alterations in the gene G6PD that result in moderately to severely decreased activity levels of the enzyme glucose-6-phosphate dehydrogenase. "POR is upregulated in G6PD deficiency, which prevents HCC cells from growing and spreading." (PMID 40465746, 2025).
hyperlipidemia (1 paper, 2023). "Wei and Zhang investigated the association of POR*28 polymorphisms and the lipid-lowering effects of atorvastatin (20 mg/d for 4 weeks) in 179 Chinese patients with hyperlipidemia." (PMID 37818163, 2023).
liver disease (1 paper, 2020). "Our data support this assumption and, importantly, are in line with our previous findings showing that a humanized bile salt pool, then induced by lack of hepatic rehydroxylation capacity due to knockout of cytochrome P450 (POR), aggravated liver disease in Mdr2−/− mice." (PMID 31979271, 2020).
lung adenocarcinoma (1 paper, 2023). A carcinoma that arises from the lung and is characterized by the presence of malignant glandular epithelial cells. "HNF4A promotes POR expression through binding to the POR’s promoter, and subsequently promotes the ferroptosis of lung adenocarcinoma." (PMID 37180584, 2023). "Restoration of POR expression blocked the promoting effect of HNF4A on ferroptosis in lung adenocarcinoma." (PMID 37180584, 2023). "To demonstrate that HNF4A promoted ferroptosis via POR in lung adenocarcinoma, we overexpressed POR in HNF4A-knockdown A549 cells, and knocked down POR expression in HNF4A-overexpressed H23 cells." (PMID 37180584, 2023). "Also, our qRT-PCR and western blot results demonstrated that HNF4A knockdown significantly reduced POR expression whereas HNF4A overexpression promoted POR expression in lung adenocarcinoma cells." (PMID 37180584, 2023). "We identified a key ferroptosis-related gene, POR serves as a potential target gene of HNF4A, whose expression was significantly changed in lung adenocarcinoma cells knocking down or overexpressing HNF4A." (PMID 37180584, 2023). "In this study, we discovered that a transcript factor called hepatocyte nuclear factor 4 alpha (HNF4A) dramatically increased cytochrome P450 oxidoreductase (POR), which in turn significantly accelerated ferroptosis in lung adenocarcinoma." (PMID 37180584, 2023). "It has not yet been shown how HNF4A affects POR expression or ferroptosis in lung adenocarcinoma." (PMID 37180584, 2023).
lung fibrosis (1 paper, 2022). "We tested the hypothesis that lung P450 oxidoreductase (POR or CPR) is important in PQ-induced lung fibrosis in mice." (PMID 35204102, 2022). "However, our findings on the role of lung POR in PQ-induced lung fibrosis suggest that POR may also contribute to PQ’s toxicity in these other organs in vivo." (PMID 35204102, 2022).
male infertility (1 paper, 2023). The inability of the male to effect fertilization of an ovum after a specified period of unprotected intercourse. "Except for the recently reported proband, no other studies focused on male infertility in patients with POR gene variants." (PMID 35842891, 2023).
Myalgia (1 paper, 2025). "There is also a separate subnetwork that is only connected to the core net via the POR gene (cytochrome P450 oxidoreductase), a leading-edge gene of the association to Myalgia." (PMID 40831500, 2025).
parasite infection (1 paper, 2021). "Thus, POR is indirectly responsible for regulation of expression of CIITA along with the molecules of MHC II group such as CD74, HLADQA1, HLADMA, HLADQB1 and HLADRB5 previously identified as genes responsible for inhibition of parasite infection." (PMID 34946170, 2021).
Primary amenorrhea (1 paper, 2021). "In conclusion, It is a third report of successful pregnancy in a PORD patient who had primary amenorrhea and different POR mutation with the published three cases who had been reported to obtain successful pregnancies after IVF." (PMID 33526062, 2021).
triple-negative breast carcinoma (1 paper, 2023). An invasive breast carcinoma which is negative for expression of estrogen receptor (ER), progesterone receptor (PR), and human epidermal growth factor receptor 2 (HER2). "The role of POR in CSCs has not been reported, although one study confirmed that in triple-negative breast cancer, high POR expression was strongly associated with shorter recurrence-free survival (RFS) and did not significantly correlate with overall survival (OS)." (PMID 37736551, 2023).
uterine disease (1 paper, 2024). "Previously identified fertility-related genes, such as POR and SCRN1, were also revealed in this study as candidate genes corresponding to uterine disease in the transition period." (PMID 38674374, 2024).
cancer (30 papers, 2013 to 2025). A tumor composed of atypical neoplastic, often pleomorphic cells that invade other tissues. "Cytochrome P450 oxidoreductase (POR), demonstrating inherent and induced susceptibility to ferroptosis, was shown to be essential for ferroptotic cell death in carcinomas." (PMID 34531924, 2021). "The association between POR polymorphisms and human cancer, however, has been rarely reported." (PMID 26123203, 2015). "Searching for additional enzymes driving lipid peroxidation, two independent studies discovered that the oxidoreductase NADPH-cytochrome P450 reductase (POR) can trigger ferroptosis in most cancer cells." (PMID 38539832, 2024). "For instance, cytochrome P450 oxidoreductase (POR) is also involved in the initiation of lipid peroxidation in multiple cancer lineages, potentially compensating for the role of LOXs." (PMID 39624080, 2024). "Intriguingly, POR is expressed in most cancer cells, suggesting an underestimation of POR's role in ferroptosis." (PMID 37840106, 2023). "A number of flavoenzymes have been implicated in the nitroreduction of CP-506 in an in vitro setting, including POR which is a major enzyme responsible for the hypoxia-selective metabolism of PR-104A in cancer cell lines." (PMID 35211015, 2022). "Cytochrome P450 oxidoreductase (POR)-enabled membrane lipid peroxide overproduction promoted ferroptosis in cancer cells under the ferroptotic inducer treatment." (PMID 36211509, 2022). "Using the CRISPR-Cas9 suppression screen, cytochrome P450 oxidoreductase (POR) was essential for ferroptotic cell death in cancer." (PMID 35547744, 2022). "In contrast, POR is broadly expressed in most cancer cells, suggesting the possible crucial role of POR in lipid peroxidation and ferroptosis." (PMID 33801564, 2021). "POR deletion was subsequently confirmed to promote strong resistance to ferroptosis induced by different FINs and in a wide range of cancer cell lines." (PMID 33539003, 2021). "Notably, POR's ubiquitous presence in various cancer cell lines suggests its potential significance in lipid peroxidation and ferroptosis." (PMID 37840106, 2023). "Cytochrome P450 oxidoreductase (POR) increases ferroptosis by upregulating peroxidation of membrane polyunsaturated phospholipids, In conclusion, metabolic pathways are able to participate in the induction of ferroptosis in cancer cells to varying degrees." (PMID 36052168, 2022). "Notably, POR is expressed at high levels in most cancer cell lines, supporting its role as a general driver of lipid peroxidation." (PMID 33539003, 2021). "Besides the context-dependent role of ALOXs in ferroptosis, recent findings suggest that the cytochrome P450 oxidoreductase (POR) also plays a role in promoting lipid peroxidation in cancer cells in an ALOX-independent manner." (PMID 34796174, 2021). "POR has previously been found to mediate iron-dependent oxidative stress-induced cell death in a variety of cancer cells, while KEAP1 may play a role in ferroptosis through inhibiting Nrf2 action since Nrf2 is a critical regulator of ferroptosis." (PMID 32788383, 2020). "In this sample of cancer patients, variation in the POR gene is estimated to account for some 11.6% of the variability in the drop of left ventricular ejection fraction (LVEF) after daunorubicin treatment, compared to the estimated 13.2% accounted for by the cumulative dose and ethnicity." (PMID 24273552, 2013). "Accordingly, a deficiency of POR promoted resistance to ferroptosis triggered by different ferroptosis-inducing agents, named FINs, in a wide range of cancer cells and lowered lipid peroxide levels without affecting the amounts of GPX4 or glutathione and cell phospholipid profiles." (PMID 38539832, 2024). "A previous study illustrated that cytochrome P450 oxidoreductase (POR), an enzyme required for electron transfer from NADPH to CYPs, was indispensable for lipid peroxidation in ferroptotic cell death of cancer cells." (PMID 36258210, 2022).
cancer (continued). "Recently, a study concluded that POR expression level was a major determinant for SN30000 activity, a new HAP, in three different cancer cell lines." (PMID 33918823, 2021).
tumor (18 papers, 2003 to 2024). "Studies have shown that POR plays an important role in energy metabolism, inflammatory immunity, and tumor development." (PMID 38685026, 2024). "To develop a mixed clonal cell line exhibiting strong POR expression for use in tumour xenograft models, we initially overexpressed full-length POR (FL POR), but this resulted in micro-heterogenous staining intensity in xenografts." (PMID 34959631, 2021). "Subsequent expression studies revealed strongly reduced cytochrome P450 oxidoreductase (POR) levels in this tumor model." (PMID 28423594, 2017). "Glucose-6-phosphate dehydrogenase (G6PD) is verified to be an independent risk factor related to the adverse outcomes of HCC, and exacerbates tumor growth, invasion, and metastasis, along with reduced ferroptosis through suppressing cytochrome P450 oxidoreductase (POR)." (PMID 37124203, 2023). "The current study is a preliminary part of a larger study, validation of the POR polymorphism-related HCC risk and prognosis in additional larger HCC cohorts, and the exact detailed mechanism by which HPN regulates tumor infiltration of immune cells in HCC are needed to verify our results." (PMID 35164791, 2022). "This conserved hypoxia-selective activity is also observed in vivo, with SN35141 treatment providing greater sterilisation of radiation-resistant hypoxic tumour cells relative to the global tumour cell population, an effect which was amplified by POR expression." (PMID 34959631, 2021). "Therefore, the expression level of POR was determined on the cellular and tumor level by western blotting and immunohistochemistry, respectively." (PMID 28423594, 2017). "This enzyme not only inhibits cytochrome P450 oxidoreductase (POR), but also promotes tumor invasion, metastasis, and growth, while decreasing ferroptosis." (PMID 39315094, 2024). "Our data suggest that evofosfamide sensitivity cannot be robustly predicted by hypoxia, MKI67, POR, or SLFN11 expression on their own, but rather is likely to be multifactorial, incorporating tumour hypoxia and other genes that influence the activation and mechanism of action of evofosfamide." (PMID 31337055, 2019). "Other candidate evofosfamide sensitivity genes—MKI67, POR, and SLFN11—did not strongly influence evofosfamide sensitivity in univariate analyses, although a weak significant relationship with MKI67 was observed, while SLFN11 expression was lost in PDX tumours." (PMID 31337055, 2019).
infection (8 papers, 2011 to 2024). The state of being infected such as from the introduction of a foreign agent such as serum, vaccine, antigenic substance or organism. "Only a little amount of endogenous POR activity was found in the cells transfected with vector alone, while the enzyme activity (i.e., POR) was significantly increased by infection of external wild-type human POR in cells." (PMID 22719896, 2012).
metabolic disorders (5 papers, 2015 to 2023). "Mutations known to control POR specificity and to cause metabolic disorders are often found in the hinge region of POR that controls conformational dynamics." (PMID 33859207, 2021). "Mutations in POR cause metabolic disorders of steroid hormone biosynthesis and affect certain drug metabolizing P450 activities." (PMID 28970799, 2017). "Mutations in POR cause a broad range of metabolic disorders." (PMID 36077536, 2022).
cardiac disease (1 paper, 2022). "This is the first report demonstrating that cardiac disease alters EET levels in human ventricular heart tissue and is associated with differential expression of proteins involved in their formation and degradation including CYP2J2, POR, and sEH." (PMID 36293289, 2022).
genetic disorders (1 paper, 2021). "POR polymorphisms may contribute this variability in clinical presentation with a given CYP21A2 defect, thus act as a secondary modifier gene, much like it occurs in other genetic disorders." (PMID 33666875, 2021).
POR also shares sentences with these, for which no sentence is quoted: craniosynostosis (3 papers); Adrenal insufficiency (2); cardiomyopathy (2); cervical cancer (2); diabetes (2); non-small cell lung carcinoma (2); retinoblastoma (2); thyroid neoplasms (2); adenocarcinoma (1); adrenal crisis (1); Alzheimer disease (1); apparent mineralocorticoid excess (1); aromatase deficiency (1); Bacterial Infections (1); Brachycephaly (1); campomelic dysplasia (1); Chagas disease (1); cholestasis (1); Cirrhosis (1); co-infection (1); colon carcinoma (1); colorectal cancer (1); COVID-19 (1); cystadenoma (1); deficient (1); degenerative diseases (1); depression (1); dyslipidaemia (1); end-stage renal disease (1); endometrial adenocarcinoma (1).
A further 26 diseases each share a sentence with POR in 1 paper.